MEFV (MEFV innate immunity regulator, pyrin)
Diseases named in the same sentence as MEFV in open-access papers (continued):
Sharing a sentence is not in itself a finding about the gene and the disease.
familial Mediterranean fever (continued). "Mutations in MEFV predispose humans to Familial Mediterranean Fever (FMF), a disease characterized by spontaneous activation of the innate immune system in the absence of a detectable pathogenic stimulus." (PMID 23226472, 2012). "The MEFV (p.E148Q) variant identified in this case has been previously reported in patients with PG and familial Mediterranean fever (FMF), but its role in PASH syndrome remains unclear." (PMID 40861239, 2025). "Although most patients recover from myocarditis, MEFV mutations in familial mediterranean fever (FMF) or STAT1 gain-of-function mutations, for example, may contribute to myocardial injury due to aberrant host immunity." (PMID 38485795, 2024). "Familial Mediterranean fever (FMF) is associated with mutations in the MEFV gene." (PMID 36677800, 2023). "Among others, mutations affecting the MEFV gene, which is responsible for familial Mediterranean fever (FMF) and encodes the protein pyrin, an essential regulator of the NLRP3 inflammasome, have been associated to an increased frequency of SpA, disregarding the HLA-B27 haplotype." (PMID 37324154, 2023). "In addition, we found a pathogenic variant in MEFV which is associated with familial Mediterranean fever and a hemizygous variant in G6PD, which is associated with X-linked hemolytic anemia." (PMID 34148116, 2022). "We also commonly observed MEFV variants, previously reported in the familial Mediterranean fever that has been associated with an exaggerated inflammatory response to infection with larger increases in WBC count, ESR and LDH levels, more pronounced tachycardia, and hypotension." (PMID 34973142, 2022). "Patients with mutations in the Mediterranean fever gene (MEFV, encoding for pyrin) have been shown to develop an autoinflammatory syndrome called Familial Mediterranean Fever (FMF) characterized by periodic fever attacks and associated with early-onset IBD-like phenotypes." (PMID 36524121, 2022). "The development of AA amyloidosis in our patient may have been related to gout, obesity, and the presence of a heterozygous complex variant for the MEFV (familial Mediterranean fever) gene." (PMID 33927906, 2021). "Additionally, gene MEFV, in which mutations have been associated with Familial Mediterranean fever (OMIM #249100), encodes the protein pyrin, which can alter the distribution of PSTPIP1 throughout the filamentous network." (PMID 34399798, 2021). "Familial Mediterranean Fever (FMF) caused by homozygous or compound heterozygous gain-of-function mutations in the Mediterranean fever (MEFV) gene, which encodes pyrin, an inflammasome protein, is an hereditary autoinflammatory disease that presents with recurrent febrile attacks and poly serositis." (PMID 32824985, 2020). "Familial Mediterranean Fever, a monogenic autoinflammatory disease secondary to MEFV gene mutations in the chromosome 16p13, is characterized by recurrent self-limiting attacks of fever, arthritis, aphthous changes in lips and/or oral mucosa, erythema, serositis." (PMID 31941537, 2020). "Familial Mediterranean fever (FMF) is a periodic fever syndrome caused by MEFV mutations." (PMID 29363386, 2018). "Familial Mediterranean fever (FMF) is a rare disease due to mutation of the MEFV gene that encodes for pyrin, a protein involved in innate immune response regulation through interactions with the inflammasome, a macromolecular complex responsible for IL-β1 production and release." (PMID 29379228, 2017). "Familial Mediterranean fever (FMF) is an autosomal recessive disease due to a MEFV gene mutation." (PMID 29379228, 2017). "Mutations in MEFV cause the autoinflammatory disorder familial Mediterranean fever (FMF)." (PMID 26589591, 2015).
familial Mediterranean fever (continued). "Familial Mediterranean fever (FMF) is an autosomal recessive disorder caused by mutations in the MEFV (familial Mediterranean fever gene, OMIM∗608107) gene and is characterized by recurrent inflammatory attacks, mainly affecting ethnic groups originating from countries around the Mediterranean Sea." (PMID 26356190, 2015). "Mediterranean Fever (MEFV) gene encodes a protein called pyrin/marenostrin that controls inflammation by interacting with the cytoskeleton in white blood cells and that, when mutated, leads to an autoinflammatory disorder called “familial Mediterranean fever”." (PMID 24868529, 2014). "Familial Mediterranean Fever (FMF) is an autoinflammatory genetic disorder causing recurrent fever episodes due to MEFV gene mutations, typically affecting small and medium-sized vessels." (PMID 39990016, 2025). "Familial Mediterranean fever (FMF) is an autoinflammatory disease characterized by MEFV mutations, leading to periodic fever with serositis." (PMID 39792323, 2025). "Familial Mediterranean fever (FMF) is an inherited autoinflammatory disorder caused by mutations to the MEFV gene, characterized by recurrent febrile episodes and serosal inflammation involving the abdomen, chest, and joints." (PMID 41300576, 2025). "Familial Mediterranean fever (FMF) is an autosomal recessive autoinflammatory disease, linked to mutations in the MEFV gene." (PMID 39143349, 2024). "Familial Mediterranean fever (FMF) is an inherited autoinflammatory disorder due to MEFV mutations; it is common in Mediterranean populations, marked by recurrent fevers and serositis." (PMID 39347254, 2024). "Familial Mediterranean Fever (FMF) is usually caused by homozygous or compound heterozygous mutations in the MEFV gene, with 30% of cases showing an autosomal dominant inheritance pattern with incomplete penetrance." (PMID 39618694, 2024). "The R202Q variant has typically been considered a benign polymorphism, unlike higher-penetrance mutations such as M694V and V726A in the MEFV gene, which are associated with more severe forms of familial Mediterranean fever (FMF)." (PMID 39458001, 2024). "Familial Mediterranean fever (FMF) is an autoimmune disease caused by mutations in the MEFV gene and is characterized by periodic fever associated with peritonitis, pleuritis, and arthritis." (PMID 37206860, 2024). "Familial Mediterranean Fever (FMF) is a genetic disease (due to a MEFV gene mutation) that causes recurrent fevers and painful inflammation of the abdomen, chest, and joints." (PMID 38790992, 2024). "Mutations in the MEFV gene can lead to familial Mediterranean fever (FMF), an autoinflammatory disease, typically inherited as an autosomal recessive disorder, characterized by recurrent fevers and serositis." (PMID 39458001, 2024). "In clinical practice, patients with PFAPA syndrome typically undergo genetic analysis targeting genes associated with monogenic autoinflammatory diseases, such as the MEFV gene, which is linked to familial Mediterranean fever (FMF)." (PMID 39085658, 2024). "Familial Mediterranean Fever (FMF) is a hereditary autoinflammatory disorder, particularly present in the Mediterranean populations, and associated with pathogenic variants in the MEFV gene." (PMID 39897620, 2024). "In addition, mutations in the MEFV gene associated with familial Mediterranean fever could further contribute to a predisposition to IgAV." (PMID 38397327, 2024). "Familial Mediterranean Fever (FMF) is a monogenic autosomal recessive autoinflammatory disorder resulting from mutations in the MEFV gene." (PMID 38465231, 2024). "Genetic variants in MEFV gene, primarily associated with familial Mediterranean fever (FMF), have been linked to various autoinflammatory conditions, including pericarditis." (PMID 39458001, 2024). "The most well-known AID is familial Mediterranean fever (FMF), which is caused by variants in the MEFV gene." (PMID 38592017, 2024).
familial Mediterranean fever (continued). "Familial Mediterranean fever (FMF) is a systemic autoinflammatory disorder caused by inherited mutations in the MEFV (Mediterranean FeVer) gene, located on chromosome 16 (16p13.3) and encoding the pyrin protein." (PMID 38892289, 2024). "Familial Mediterranean Fever (FMF) is an autosomal recessive autoinflammatory disease caused by mutations in the MEFV (MEditerranean FeVer) gene that affects people originating from the Mediterranean Sea." (PMID 38409042, 2024). "Familial Mediterranean fever (FMF) is a genetically determined autoinflammatory disease transmitted mostly by an autosomal recessive mechanism and caused by point mutations of the MEFV (Mediterranean FeVer) gene." (PMID 39684669, 2024). "Macrophages derived from iPS cells of familial Mediterranean fever (FMF) patients with the MEFV gene mutations displayed pro-inflammatory phenotypes." (PMID 37876023, 2023). "Pyrin is encoded by MEFV, and mutations in MEFV are present in patients with familial Mediterranean fever (FMF)." (PMID 37895853, 2023). "Positive molecular testing for mutations in the familial Mediterranean fever (MEFV) gene contributed to the diagnosis of FMF, which was based on the Tel-Hashomer clinical criteria." (PMID 37575846, 2023). "In 1997, the French Familial Mediterranean Fever (FMF) Consortium first reported a monogenic disease characterized by fever and multisystem inflammation, i.e., FMF caused by MEFV mutations." (PMID 35123508, 2022). "Considering the mediterranean origin of the family we sought to investigate the MEFV Gene and found a homozygous single nucleotide mutation strongly associated with familial mediterranean fever (FMF)." (PMID 36096831, 2022). "Thus, for example, the pathogenic variants in the Mediterranean fever (MEFV) gene might predispose to IgAV in patients with familial Mediterranean fever (FMF) and may be associated with different clinical presentation of IgAV in countries where FMF is common." (PMID 35372148, 2022). "Familial Mediterranean fever (FMF) is caused by the dysfunction in pyrin, which is encoded by the MEFV gene located on chromosome 16." (PMID 35190906, 2022). "In addition, studies have shown that mutations of MEFV gene which encode the pyrin protein could cause Familial Mediterranean fever." (PMID 35909123, 2022). "Mutations in the MEFV gene have been linked to autoinflammatory diseases such as familial Mediterranean fever (FMF) or pyrin-associated autoinflammation with neutrophilic dermatosis (PAAND)." (PMID 36014040, 2022). "In 1997, several groups disclosed that the mutations of the MEFV gene in humans are responsible for the monogenic autoinflammatory disease familial Mediterranean fever (FMF)." (PMID 35883561, 2022). "Familial Mediterranean fever (FMF) is the most common monogenic auto inflammatory disease, mainly affecting people from Mediterranean countries and associated with mutations in the MEFV gene." (PMID 36388918, 2022). "Familial Mediterranean fever (FMF) is caused by mutations in the MEFV gene, which codifies for the Pyrin inflammasome." (PMID 33803783, 2021). "Familial Mediterranean fever (FMF) is an autoinflammatory disease with autosomal recessive inheritance, resulting from mutations in the Mediterranean Fever (MEFV) gene found on chromosome 161,2." (PMID 33436947, 2021). "Mutations in MEFV cause inflammatory syndromes including Familial Mediterranean Fever (FMF) and Pyrin-Associated Autoinflammation with Neutrophilic Dermatosis (PAAND)." (PMID 34854899, 2021). "Since the identification of MEFV, a gene causing Familial Mediterranean Fever (FMF) once mutated, many monogenic AIDs have been identified over the past two decades assisted by the development of genetic sequencing technologies." (PMID 33042144, 2020). "Familial Mediterranean fever (FMF), the most common auto‐inflammatory disease, is an autosomal recessive disease caused by a mutated MEFV gene." (PMID 32608157, 2020).
familial Mediterranean fever (continued). "The African elephant lost MEFV, a gene that is linked to the autoinflammatory disease familial Mediterranean fever (FMF)." (PMID 33575564, 2020). "Genetic screening for Familial Mediterranean Fever (FMF) showed compound heterozygous variants of uncertain significance in exon 3 of the MEFV gene, p.P369S and p.R408Q." (PMID 31660995, 2019). "The distribution of Mediterranean fever (MEFV) gene mutations in Turkish familial Mediterranean fever (FMF) patients varies according to geographic area of Turkey." (PMID 30887796, 2019). "Rare polymorphisms of MEFV, which encodes the protein pyrin, are known to cause Familial Mediterranean Fever (FMF), a monogenic, autosomal recessive, autoinflammatory disease which can be complicated by arthritis." (PMID 30946743, 2019). "Mutations in the MEFV gene were firstly identified for patients with familial Mediterranean fever (FMF) in 1997." (PMID 32082075, 2019). "Familial Mediterranean Fever (FMF) is a monogenic autoinflammatory disease, secondary to mutations of MEFV gene, typically expressed with recurrent attacks of fever, serositis, rash, aphthous changes in lips and/or oral mucosa." (PMID 31627741, 2019). "Familial Mediterranean fever (FMF) is the most common autoinflammatory disorder characterized by periodic fever and polyserositis caused by MEFV mutations." (PMID 29363386, 2018). "On the other hand, Familial Mediterranean Fever (FMF), the most common form of the autoinflammatory disorders, is associated with autosomal recessively inherited variants in exon 10 of the MEFV gene, which encodes the pyrin protein." (PMID 30386349, 2018). "Pyrin has been identified as a causative gene of the MEFV product of familial Mediterranean fever (FMF), an autosomal recessive inherited autoinflammatory syndrome." (PMID 29259708, 2017). "Familial Mediterranean Fever (FMF) is an autoinflammatory disorder caused by mutations in the MEFV gene." (PMID 29178647, 2017). "Mutations in MEFV are associated with the autoinflammatory disease Familial Mediterranean Fever (FMF)." (PMID 27000047, 2016). "The most frequent disease among HPF is familial Mediterranean fever (FMF), caused by mutations in the MEFV gene, encoding a protein named pyrin, which is mainly expressed in the inflammatory cells." (PMID 26357457, 2015). "Familial Mediterranean fever (FMF) is an inherited autosomal recessive disorder, ethnically restricted and commonly found among individuals of Mediterranean descent, caused by MEFV gene mutations on chromosome 16." (PMID 23865042, 2013). "In a search for possible candidate genes for FMS with an inflammatory basis, we became interested in the MEFV gene, in which a number of mutations cause Familial Mediterranean Fever (FMF)." (PMID 23762283, 2013). "In a search for possible candidate genes that are associated with conditions such as inflammation of the bowel, as well as other organs, we became interested in the gene MEFV, in which a number of mutations cause Familial Mediterranean Fever (FMF)." (PMID 20041150, 2009). "Mutations in MEFV lead to the autoinflammatory disorder, familial Mediterranean fever (FMF, MIM249100), which is characterized by recurrent self-resolving attacks of fever and polyserositis, with no clinical signs of disease in remission." (PMID 18725973, 2008). "These factors were IL-1β, prostaglandin-endoperoxide synthase 2 (PTGS2/COX-2), NOD-like receptor family CARD domain-containing protein 4 (NLRC4), Familial Mediterranean Fever (MEFV) gene, and caspase 5 (CASP5)." (PMID 40861543, 2025). "MEFV is the gene of familial Mediterranean fever (FMF) (IM #134610/249100), one of the most common monogenic autoinflammatory diseases." (PMID 40725177, 2025). "Despite the presence of all clinical diagnostic criteria for Familial Mediterranean Fever (FMF) and a heterozygous mutation (p.V726A) in the Mediterranean Fever (MEFV) gene, the atypical presentation of these symptoms prompted a comprehensive genetic examination." (PMID 41158762, 2025).
familial Mediterranean fever (continued). "Homozygous MUTYH PVs are associated with colorectal cancer and adenomatous polyposis while homozygous PVs in MEFV cause Familial Mediterranean Fever (FMF), a relatively prevalent disease in people who live around the Mediterranean region, including the Druze population." (PMID 37107695, 2023). "Familial Mediterranean Fever (FMF) is the most frequent monogenic auto-inflammatory disease, secondary to mutations in the MEFV gene." (PMID 36198677, 2022). "It is intriguing that Brucella downregulates macrophage MEFV expression, the gene responsible for familial Mediterranean fever, the prototype IL-1β-mediated autoinflammatory disease." (PMID 35979363, 2022). "Gain-of-function mutation in the MEFV gene can lead to familial Mediterranean fever (FMF)." (PMID 35655291, 2022). "The prototypic SAID is familial Mediterranean fever (FMF), an autosomal recessive disease caused by mutations in the MEFV gene that result in overactivity of the pyrin inflammasome and interleukin (IL)‐1β secretion, which presents with episodic serositis." (PMID 35658515, 2022). "Most studies suggest that patients with familial Mediterranean fever (FMF, the disorder caused by MEFV gene mutations) are at an increased risk of IgAV." (PMID 36263029, 2022). "Patient 4 is a 15-year-old girl who has had familial Mediterranean fever (MEFV p.M694V homozygous) for 3 years treated with canakinumab 150 mg/month and colchicine." (PMID 33562758, 2021). "Familial Mediterranean fever (FMF); is an autosomal recessively inherited autoinflammatory disease caused by the mutations in the Mediterranean Fever (MEFV) gene." (PMID 33436947, 2021). "Familial Mediterranean Fever (FMF) is a genetic autoinflammatory disease characterized by recurrent episodes of fever and serositis caused by mutations in the MEFV gene, while Multiple Sclerosis (MS) is an inflammatory demyelinating disease of the CNS with genetic and environmental etiology." (PMID 33584496, 2021). "Familial Mediterranean Fever (FMF) is the prototype of hereditary autoinflammatory disorders and caused by mutations on the MEFV gene located on the short arm of chromosome 16." (PMID 33726481, 2021). "FMF (Familial Mediterranean Fever) results from a breakdown in regulation of inflammasome activity caused by mutations in the MEFV gene which encodes pyrin." (PMID 35003136, 2021). "Familial Mediterranean Fever (FMF) is an example of monogenic autoinflammatory disease due to MEFV gene pathogenic variants that lead to a dysfunctional hyperactive state of the pyrin protein eliciting proinflammatory cytokine release and pyroptosis (cell death)." (PMID 32899315, 2020). "Next, we aimed to reduce the number of VUS variants (88% of the dataset) with the same strategy already utilized to improve MEFV gene variants classification in Familial Mediterranean Fever (FMF), a disease where clinical misdiagnosis can be as frequent as in NF1." (PMID 31979111, 2020). "Methylation patterns in the MEFV exon in pediatric patients with Familial Mediterranean Fever correlated with expression of the same gene; the observed slight increase in DNA methylation of the second exon in patients correlated with decreased expression." (PMID 32793186, 2020). "Twenty-four patients had a MEFV mutation [(familial Mediterranean fever (FMF)], which belongs to the main category autoinflammatory disorders, and 20 patients had a defect in C1 Inhibitor (complement deficiency), which belongs to the main category of complement deficiencies." (PMID 31379802, 2019). "Mediterranean fever (MEFV) gene mutations are associated with familial Mediterranean fever (FMF)." (PMID 31682063, 2019). "Conflicting reports exist on the number of NK cells in patients with familial mediterranean fever (FMF, mutation in MEFV, resulting in abnormal regulation of IL-1β activation)." (PMID 32010140, 2019).